CD4 (CD4 molecule)
Diseases named in the same sentence as CD4 in open-access papers (continued):
Sharing a sentence is not in itself a finding about the gene and the disease.
tumor (continued). "Based on immunohistochemical staining, the phenotype of the tumor cells was CD3+, CD43+, CD56+, TIA-1+, CD30+, CD4-, CD5-, CD7-, CD8-, CD20- and CD79a-." (PMID 26126576, 2015). "An essential asset for creating a potent anti-tumor immunity is the activation of DCs and consecutively cytotoxic CD8+ T lymphocytes (CTL) alongside with CD4+ T lymphocytes." (PMID 26500646, 2015). "However, after the tumor challenge, all CD4+ T cell subsets in blood had sharp increases at the early stage and then followed to rapidly drop down at the middle or late cancer stages in 4T1 and E0771 tumor-bearing mice, suggesting the hematological changes of CD4+ T cell subsets." (PMID 25968569, 2015). "The tumor secretes chemokines CXCL8, CCL2, IL-1, and TNF-α that recruits macrophages and suppressive CD4+CD25+CD127lowFOXP3+ Tregs to the tumor site." (PMID 25972872, 2015). "As AMPK was specifically deleted in CD4+ and CD8+ T cells, we focused on analyzing T cell presence and functions in the tumor stroma." (PMID 25760243, 2015). "Sa and co-workers showed that curcumin is effective in restoring populations of CD4+ and CD8+ cells in the tumor microenvironment and thereby driving the Th2 cytokine bias towards a Th1 type response again." (PMID 26464579, 2015). "Here, we show that SUSD4 is expressed by epithelial tumor cells, in which it affects migration and invasion, and in tumor-infiltrating CD8+ and CD4+ T cells." (PMID 26480818, 2015). "In the tumor microenvironment (TME), the IFN-γ released by NK cells stimulates CD4+ T cells to polarize toward a Th1 subset and accelerates the development of activated macrophages and cytotoxic, tumor-targeting CD8+ T cells." (PMID 26697006, 2015). "In contrast, depletion of CD8+ T cells, either alone or in combination with CD4+ T cells, restored SCC FAK−/− tumor growth." (PMID 26406376, 2015). "In the immunosuppressive tumor microenvironment, blocking CTLA-4 has the potential to directly activate CD4+ and CD8+ effector T cells, leading to tumor clearance." (PMID 25806106, 2015). "In the tumor bed of low- and high generation xenografts which underwent rejection, ED1+ macrophages and microglia were numerous, together with CD4+ and CD8a+ lymphocytes." (PMID 26291724, 2015). "THBS1 secreted by CD4+ and CD8+ T cells can negatively regulate angiogenesis in a tumour-bearing mice model." (PMID 25652121, 2015). "Effector CD4+ and CD8+ T cells play important roles in the host’s anti-tumor immune responses as they facilitate destruction of tumor cells." (PMID 25629611, 2015). "Conversely, CD4+ forkhead box P3 (FOXP3+), CD4+ Th2 cells, M2 macrophages, and myeloid-derived suppressor cells (MDSCs) promote tumor growth." (PMID 26300242, 2015). "We found similar trends of CD4+ and CD8+ T cells in bloods as those in TILs, showing significantly increased CD4/CD8 T cell ratios with the advanced tumor stages both in 4T1 and E0771 mouse models." (PMID 25968569, 2015). "A unique feature of DV is that primary infections result in activation of a TH1-type response of CD4+ and CD8+ helper-inducer and cytotoxic-effector CTL, which is also an effective phenotype for tumor immunotherapy." (PMID 25592450, 2015). "Although infiltrating CD4+ Th1 cells and CD8+ cytotoxic T cells sign a positive prognosis in CRC, these lymphocytes often can't kill tumor cells." (PMID 26008981, 2015). "Immune suppression in the tumor microenvironment is fundamentally mediated by CD4+CD25+FoxP3+ regulatory T cells (Tregs), as the major mechanism of tumor immune escape, a crucial hurdle for tumor immunotherapy." (PMID 26029105, 2015). "Many researchers have found that CD4 + CD25+ regulatory T cells (Tregs) population increased in both the peripheral blood and tumor microenvironment in HCC patients, which correlates with a poor prognosis." (PMID 25889022, 2015).
tumor (continued). "The data of these cells in NSCLC are relatively rare and controversial therefore we aimed to evaluate the infiltration patterns of Foxp3+CD4+, CD4+ and CD8+ T cells in tumor islets and stroma from patients with NSCLC and to analyze their relations to survival." (PMID 26604855, 2015). "The increased survival rates correlated with increased frequencies of tumor-reactive CD8 and CD4 T cells." (PMID 25614821, 2015). "Tumor cells by themselves secrete TGF-beta, IL-10, VEGF, PGE2 that induce DCs to secrete more TGF-beta contributing to the conversion of CD4(+) T cells to Treg phenotype, enhancing the cellular immune suppression once more." (PMID 32309563, 2015). "Curcumin efficiently restored CD4+ and CD8+ populations in all immune compartments of tumor-bearing mice." (PMID 26464579, 2015). "In the case of RMA tumour in aged mice, IFN-γ response of tumour (MuLV EnvH13.3)-specific CD4+ T cells was restored by IL-6 blockade." (PMID 25850032, 2015). "The authors found that IL-12 administration triggered a profound increase in all tumor-infiltrating lymphocyte (TIL) populations, including CD3+CD4+ T helper cells (Th), CTL, and CD4+CD25+ regulatory T cells (Treg)." (PMID 26404357, 2015). "In the elimination phase of cancer immunoediting, specific CD4+ and CD8+ T-cells infiltrate the tumour site and are thought to participate in killing of antigen-positive tumour cells." (PMID 26606748, 2015). "Our results also suggest that tumor-infiltrating CD4+ and CD8+ T cells have distinct roles for control of tumor progression and clinical outcomes." (PMID 25968569, 2015). "For example, CD4 T cells can promote progression through interaction with tumor-specific macrophages, which subsequently stimulate the EGFR pathway leading to tumor metastasis." (PMID 25991675, 2015). "Effective immunological eradication of tumors requires NK cells and tumor-specific CD8+ and CD4+ T cells." (PMID 26379663, 2015). "Whereas, host BM-derived APC appear to be required for CD4+ T cell tolerance in lymphoma models; it appears CD8+ T cells directly interact with antigen-expressing tumor cells." (PMID 26082776, 2015). "Subsequently, they demonstrated increased frequencies of tumor-infiltrating IFN-α producing effector T cells and a marked increase in the ratio of CD4+ effector T cells to CD4+ Foxp3+ Tregs." (PMID 25682197, 2015). "Cell depletion experiments pinpoint to a pivotal role of both CD4+ and CD8+ effector T cells in tumor protection conferred by combination treatment since removal of each subset significantly attenuated the protective effect." (PMID 26219551, 2015). "In our previous studies, immunohistochemistry assays showed the numbers of DCs, CD4+ and CD8+ T cells distributed in the tumor tissues increased gradually after topical PDT." (PMID 25915530, 2015). "CD4+ and CD8+ T cells are the main types of lymphocytes in cell-mediated immunity and play a central role in the anti-tumor immune responses." (PMID 25605488, 2015). "Ligation of OX40 on T cells with its ligand on APCs results in activation of both CD4+ and CD8+ T cells, leading to inhibition of tumor growth." (PMID 26350600, 2015). "Systemic induction of Tregs was also observed clinically, as CD4+CD25+FoxP3+CD127 low cells were markedly increased in the peripheral blood of NHL patients and correlated with tumor burden." (PMID 25941795, 2015). "The tumor cells of BPDCN and PPDM share the common characteristic phenotype of pDCs: lin−, CD4+, CD68+, CLA+, CD123+, BDCA2+, Bcl11A+ and CD2AP+." (PMID 25779340, 2015). "Forexample, in patient 27, whose bone marrow had only one clonalDβ–Jβ rearrangement, the surface of the tumor cells did nothave CD3, CD5, CD4, or CD8, but only CD2 and CD7." (PMID 26483968, 2015). "Specifically, this combination therapy induced robust effector CD4 and CD8 T cell responses necessary to induce tumor regression." (PMID 25763356, 2015).
tumor (continued). "Both spleen and bone marrow-derived CD4 and CD8 T cells showed a significant increase in tumor-specific IFN-γ producing cells when mice were treated with anti-PD-L1 in combination with anti-TIM-3, or anti-LAG-3 or anti-CTLA4 as compared to anti-PD-L1 alone." (PMID 25614821, 2015). "In the early stages of tumor development (before 16 days in 4T1 and 22 days in E0771 models), CD8+ T cells were more dominant than CD4+ T cells in TILs; while the reversed proportion was observed in the late stages of tumor development." (PMID 25968569, 2015). "This therapeutic strategy currently recommended is highly effective favouring the reduction of the HIV viral load, the increase of the CD4 T-lymphocyte count, and the decrease of the occurrence of the HIV-related tumours, such as KS." (PMID 25755902, 2015). "Tumor-specific CD4+ and CD8+ T cells migrate to the tumor site, and CTLs induce cell lysis and/or apoptosis in antigen-bearing tumor cells through the release of perforin and granzymes or by a Fas/Fas ligand interaction." (PMID 25756279, 2015). "CD4+ CD25+ regulatory T-cells (Tregs), constituting approximately 5–10% of peripheral CD4+ T cells play an important role in tumour immune evasion." (PMID 26137480, 2015). "Collectively, these results suggest a significant interaction between CD4+ and CD8+ T cell subsets is required with an essential role for both in effectively mediating anti-tumor responses." (PMID 25901284, 2015). "CD4 T cells from mice treated with WBI and immune checkpoint blockade were also analyzed for cytokine production in response to tumor cells in vitro." (PMID 25614821, 2015). "Gene expression of CD4 and FOXP3 showed minimal variability between tumours in all examined profilers and were excluded from further cluster analysis." (PMID 25970543, 2015). "The immune cells of this subset of patients can be activated to pronounced IL-2 production resulting Nap-specific expansion of CD4+ and CD8+ T cells which probably is a prerequisite for optimal Nap induced anti-tumour effects." (PMID 25669986, 2015). "CD4+ T cells orchestrate the activity of many other cell types including macrophages, NK cells, B cells, DCs, and CD8+ T cells or act on tumor cell survival by intratumoral secretion of inflammatory cytokines like IFN-γ." (PMID 26844233, 2015). "Occasional tumor biopsies of recurrent CM showed brisk lymphoid infiltration, mainly composed of CD8+, CD4+, and CD20+ lymphocytes with few Treg cells, and striking evidence of tumor-cell killing by CD8+ and CD4+ lymphocytes." (PMID 25859247, 2015). "We have performed the correlation analysis for proportions of CD4, CD8, and CD56 cells with patient's tumor type, cytokine production, and toxicity." (PMID 26515587, 2015). "As expected, numbers of CD4+ T cells, CD8+ T cells and CD4+FoxP3+ T regulatory cells were reduced 3 days after Cy administration (day 11 post tumor inoculation)." (PMID 26082836, 2015). "In order to stimulate CD4 Th1 responses in cancer patients, increasing attention has been focused on identifying MHC class II-restricted epitopes from relevant human tumor antigens to actively target these cells for cancer vaccine." (PMID 26350591, 2015). "At 14 days after Cy administration (day 22 after tumor inoculation), there was greater expansion of CD8+ T cells and CD4+ T regulatory cells in mice treated with Cy and lysate/CpG as compared to Cy only." (PMID 26082836, 2015). "Mice receiving anti-Asialo-GM1 antibody in addition to ACT still experienced tumor recurrence, although to a lesser extent than animals receiving TRP-1-specific CD4+ T cells alone." (PMID 26405570, 2015). "In all these experiments, both CD4-positive and CD8-positive T cells were required for the induction of antitumor immunity and both CD4-positive and CD8-positive tumor-infiltrating T cells (TILs) expressed OX40." (PMID 26579494, 2015).
tumor (continued). "In the case of tolerance, leukocytes, therein CD4+ and CD8+ T cells fail to invade the tumor bed and are found only around tumor blood vessels." (PMID 26291724, 2015). "At baseline patient R356 had more (CD3 x33, CD4 x10, CD8 x9, CD11c x21, CD68 x15, CD163 x12) immunological cells in the tumor than patient O340." (PMID 25714011, 2015). "The authors demonstrated that resident DCs in the lymph nodes selectively took up the mRNA following intranodal injection, and induced potent antigen-specific CD4+ and CD8+ T cell responses in tumor-bearing mice." (PMID 26343191, 2015). "To determine the effect of the combination vaccine on tumour growth and tumour-infiltrating lymphocytes (TIL), we analysed CD4+ and CD8+ T cell populations." (PMID 26085010, 2015). "IL-1β is required for efficient priming of CD4+ T cells and interferone-γ (IFN-γ) producing tumor antigen-specific CD8+ CTLs and therefore for the generation of an anti-tumor immune response." (PMID 26500646, 2015). "The expression of genes in tumours was low for CD3Z, CD8, CXCL13, SNAI2 and ESR1 (40-DCq <32) and moderate for IGHM, CD4, CXCL9 and FOXP3 (40-DCq 32–35)." (PMID 25970543, 2015). "When the frequencies of CD4+ CXCR3+ T cells were compared among the input and migrated fractions recovered from the tumour, a significant enrichment of CXCR3+ CD4+ T cells was found P = 0·009." (PMID 25495686, 2015). "It is known that CD4+ T helper 1 (Th1) cells, CD8+ cytotoxic T cells, NK cells, M1 macrophages, and DCs are protective against tumor growth." (PMID 26300242, 2015). "During in vivo tumor growth, sensitization of CD8 T cells in the TDLN occurs independently from sensitization of CD4 T cells." (PMID 26090481, 2015). "It was found that the numbers of CD4+CD25+ regulatory T cells in spleen, thymus, and tumor were lower in the FYN group than in the model group (P < 0.05)." (PMID 26161392, 2015). "Stimulation of CD40 on APCs is through CD40L expression on helper CD4+ T cells which can activate and “license” the APCs to prime CD8+ T cell responses, and lead to enhanced tumor protection." (PMID 25825910, 2015). "Whole tumor cells as a rich source of antigens expresses the epitopes for CD8+ cytotoxic T cells and CD4+ T helper (Th) cells." (PMID 25801067, 2015). "In a mouse cancer model, CD4+CD25+ Tregs inhibited NKG2D-mediated NK cell cytotoxicity by TGF-β release and subsequent tumor rejection and metastasis inhibition." (PMID 26220086, 2015). "Combination therapy led to changes in the tumor microenvironment including increases in CD8 T cell infiltration as well as significantly increased CD8/Treg, CD4 Teff/Treg, and CD8/MDSC ratios, which favor tumor clearance and successful treatment." (PMID 26106583, 2015). "In tumor-free C57BL/6 and BALB/c control mice, there were very limited proportions of CD4+ T cell subsets in peripheral blood." (PMID 25968569, 2015). "Similar to MDSCs that accumulate during tumor progression, resident peritoneal macrophages from NTB mice abrogated anti-CD3/B7.1-stimulated CD4+ and CD8+ T cell proliferation." (PMID 25888637, 2015). "CD4+ and CD8+ cell content at the point -7 days and point 0 days was measured before DC vaccination and tumor transplantation thus correspond to baseline of healthy mice." (PMID 26325576, 2015). "Several studies found a favorable prognostic effect of concurrent infiltration by CD4+ and CD8+ T cells, as well as NK cell density at the tumor mass." (PMID 25801067, 2015). "We next measured the frequency of CD4+, CD8+, and CD11b+/Ly6G+ cells in BALF of tumor-bearing WT and iNOS-KO mice at 3 day after GalCer administration." (PMID 26496031, 2015). "After polyclonal expansion of tumor-specific CD8+ and CD4+ cells, the SLN-T cells can be safely transfused back into patients as an adjuvant to current standard treatment regimens for CRC." (PMID 25990075, 2015).
tumor (continued). "The percentage of CD3+CD4+ T cells distribution was significantly increased in OSCC patients with T3–4 tumor size (42.39 ± 5.49), compared to that with T1–2 tumor size (29.06 ± 3.44)." (PMID 26587366, 2015). "DCs present the tumor peptides via MHC complexes and deliver co-stimulatory signals to naïve CD4 and CD8 T cells." (PMID 25980578, 2015). "Taken together, these results suggest that both CD4+ and CD8+ T-cells are required for immunity and effective tumor cell elimination following combination immunotherapy." (PMID 26079374, 2015). "In an ovarian cancer model, co-administration of a PD-L1 antagonist with α4-1BB and a cellular vaccine expressing GM-CSF (GVAX) let to increases in both CD4 effector and CD8 T cell infiltrates into the tumor with a concomitant decrease in regulatory T cells." (PMID 26106583, 2015). "CD4+ and CD8+ T cells and NK cells are the principal IFN-γ-producing cells, and their anti-tumor activity depends on the robustness of IFN-γ production." (PMID 24884733, 2014). "In previous studies, we reported that anti-neu antibody can induce anti-tumor CD8+ and CD4+ T cell responses." (PMID 25179116, 2014). "Importantly, the in vivo anti-tumor effects of IT were also not diminished in CD4 deficient mice." (PMID 25119341, 2014). "Loss of inflammassome function in mice resulted in decreased presence of natural killer (NK), dendritic (DC), CD4+, CD8+ and CD45RB+ T cells in the tumor lesions as well as in lymph nodes (LN) compared with WT mice." (PMID 25268644, 2014). "Significant work investigating the M1/M2 polarization axis and similar pathways involved in dendritic cell, CD4+ T-cell and CD8+ T cells programing in the tumor microenvironment is ongoing." (PMID 25505736, 2014). "This vector can deliver multiple antigens into the MHC class I and II antigen presentation pathways to stimulate potent CD4+ and CD8+ T cell responses, and can break immunological tolerance to tumor antigens in transgenic mouse models." (PMID 25051027, 2014). "In contrast, Nrp1 was expressed on CD4+ and even more so on CD8+ TIL in a majority of patient tumor samples." (PMID 25343644, 2014). "Accordingly, the chaperones and components regulating these pathways are often targeted by tumors to escape the tumor surveillance enforced by CD8+ and CD4+ T lymphocytes." (PMID 29250602, 2014). "Natural killer (NK) cell activity and the number of CD4+ and CD8+ T lymphocyte cells in the peripheral blood of tumor-bearing mice were increased by Ad-hLF." (PMID 24520300, 2014). "We found that PC3 and MCF7 tumor cells dramatically increased phosphorylation of LCK, PKA, and CREB in senescent CD4+ T cells, suggesting that tumor cell treatment induced LCK inhibitory signaling in senescent T cells." (PMID 25231413, 2014). "Vaccination resulted in the expansion of myeloma-specific T cells in a majority of patients as manifested by the percent of CD4 and/or CD8 T cells expressing IFNγ following ex vivo exposure to autologous tumor lysate." (PMID 25386340, 2014). "We found that synthetic Poly-G3 and natural TLR8 ligand (ssRNA40) completely reversed the suppressive functions of naturally occurring CD4+CD25+ Treg, and tumor-derived CD4+, CD8+, and γδ Treg cells." (PMID 25231413, 2014). "CD4+CD25+ Treg-depleting approaches have revealed that reduced Treg numbers improve anti-tumor responses and the inhibition of tumor growth." (PMID 24642245, 2014). "As a mechanism of Treg recruitment to tumors, it has been proposed that the tumor cells and tumor infiltrating macrophages produce the chemokine CCL22, which attracts and recruits CD25+ CD4+ Tregs expressing CCR4." (PMID 25080123, 2014). "First, we recently demonstrated that human TLR8 signaling completely reversed the suppressive functions of naturally occurring CD4+CD25+ Treg cells and tumor-derived CD4+, CD8+, and γδ Treg cells." (PMID 25231413, 2014).